NTSR1 (neurotensin receptor 1)
Diseases named in the same sentence as NTSR1 in open-access papers (continued):
Sharing a sentence is not in itself a finding about the gene and the disease.
tumor (continued). "NTS effects on EMT induction and tumor invasion are mediated by aberrant activation of both the NTSR1 and Wnt/β-Catenin pathways." (PMID 33268796, 2020). "In tumor tissues, NTS and NTSR1 expression is higher than in healthy ones and is associated with poor prognosis." (PMID 33268796, 2020). "The NT/NTSR1 complex enhances tumour aggressiveness by increasing human epidermal growth factor receptor (HER) expression and activation via the release of specific EGFR, HER2 and HER3 ligands." (PMID 32336282, 2020). "When it comes to NTSR1, the use of radioligand therapy with NTSR1-targeting agent, 177Lu-3BP-227, inhibited tumor growth and decreased its volume by 55–88%." (PMID 32429087, 2020). "In vitro evidence supported NTS induced activation of tumour growth and migration pathways which were mitigated by NTSR1 antagonisation with SR48692." (PMID 32764278, 2020). "High NTSR1 in patients with IDCs is correlated with larger tumor size, Scarff-Bloom-Richardson (SBR) histoprognostic grade 3 and number of positive lymph nodes." (PMID 32336282, 2020). "Mouse model studies also showed promotion of tumor growth through stimulating action of NT/NTSR1 on the expression of miR-21 and miR-155 in colonocytes via AKT and NF-κB signaling." (PMID 32429087, 2020). "By labeling such NT derivatives with radioactive isotopes or cytostatic drugs, such drugs specifically destroy tumor cells that overexpress NTSR1." (PMID 29467963, 2018). "Tissue from lymphovascular invasion showed even higher intensity of expression of NTSR1 than the rest of the tumour." (PMID 28316623, 2017). "Altogether, this hybrid nanoparticle delivery system can be used as a platform technology for intracellular delivery of siRNAs to NTSR1-overexpressing tumor cells." (PMID 26410728, 2015). "NTS and NTSR1 are neuropeptide-receptor complexes which are frequently deregulated during tumor progression." (PMID 26298774, 2015). "Functional analysis suggested that NTSR1 expression promotes tumor growth and invasion, which is consistent with the better prognosis of patients with NTSR1 methylation." (PMID 26334593, 2015). "This prompted us to examine the genetic and epigenetic alterations occurring to NTSR1 during tumor progression by analyzing a mixed colorectal lesion consisting of adenomatous and malignant portions." (PMID 26334593, 2015). "Correspondingly, immunohistochemical analysis of the same tumor specimens showed low and elevated levels of NTSR1 protein in the adenomatous and cancerous regions, respectively." (PMID 26334593, 2015). "This hybrid nanoparticle delivery system can be used as a platform technology for intracellular delivery of siRNAs to NTSR1-overexpressing tumor cells." (PMID 26410728, 2015). "Here we report that the NTS/NTSR1 complex contributed to tumor aggressiveness when it is abnormally over-expressed in tumors." (PMID 25249545, 2014). "We show that neurotensin (NTS) and its high affinity receptor (NTSR1) contribute to the enhancement of experimental tumor growth and metastasis emergence in an experimental mice model." (PMID 25249538, 2014). "In agreement with in vitro studies, tumor growth induced by NTS/NTSR1 can be restrained by a specific tyrosine kinase inhibitor EGFR and HER2, lapatinib." (PMID 25249538, 2014). "We propose the use of NTS/NTSR1 tumor expression, as a biomarker for the use of EGFR tyrosine kinase inhibitors in patients lacking EGFR mutation." (PMID 25249545, 2014). "In this article we show that the NTS/NTSR1 complex enhances tumor aggressiveness (tumor growth and metastasis emergence) by enhancing HERs expression, and their activation by the release of specific EGFR and HER3 ligands." (PMID 25249538, 2014). "For example, NTSR1 inhibition efficiently sensitized prostate regulation in orthotopic human tumor xenografts in mice to radiotherapy by significantly reducing tumor size, and in prostate cancer cells bearing NTS autocrine regulation." (PMID 23335914, 2012).
tumor (continued). "By using NTSR1 Sh-RNA and SR 48692, tumor growth was significantly decreased when NTSR1 expression was abolished or blocked in experimental tumors of the breast." (PMID 23335914, 2012). "Firstly, NTSR1 can be targeted with radio-labeled NT analogues for whole body tumor imaging and possibly even for subsequent therapeutic interventions." (PMID 21364741, 2011). "NTSR1 staining in IDCs showed that NTSR1 expression was spread throughout many tumor cells in the invasive and ductal components." (PMID 19156213, 2009). "In parallel, we observed a frequent regional co-localization of both markers in adjacent tissue sections from the same tumor, suggesting NTSR1 activation." (PMID 19156213, 2009). "The high expression of NTSR1 is associated with the SBR grade, the size of the tumor, and the number of metastatic lymph nodes." (PMID 19156213, 2009). "Multivariate analysis with a Cox model adjusted for major prognosis risk factors, age, tumor size, SBR grade, positive ER status and lymph nodes, showed that high NTSR1 expression remained an independent prognosis marker." (PMID 19156213, 2009). "High NTSR1 expression was significantly associated with the SBR grade, the size of the tumor, and the number of metastatic lymph nodes, and ultimately with death of the patients." (PMID 19156213, 2009). "Overall, this study identifies [68Ga]-Ga-SK01014 as a promising NTSR1-targeted imaging agent with improved renal clearance and provides insight into the balance between stability and receptor-driven tumor uptake, guiding the future design of neurotensin-based theranostic agents." (PMID 42206223, 2026). "The regulatory role of NTS/NTSR1 signaling in tumor progression has been comprehensively reviewed." (PMID 41556039, 2026). "In our previous work based on the lead SR 142948A, we developed the first 18F-fluoroglycosylated NTSR1 antagonist (Ki (NTSR1) = 0.98 nM) with excellent biodistribution, rapid clearance from blood, and specific NTSR1-mediated tumor uptake in HT-29 tumor-bearing mice, as demonstrated by PET imaging." (PMID 40574013, 2025). "In the SPECT/CT imaging of HT-29 tumor xenografts, [99mTc]1 showed a higher NTSR1-specific tumor uptake than [99mTc]2 at all time points after tracer injection, with 12 ± 2.8 %ID/g for [99mTc]1 vs. 3.1 ± 1.1 %ID/g for [99mTc]2 at 4 h p.i. and adequate tumor-to-background ratios." (PMID 40574013, 2025). "However, the presence of low accumulation in the tumor and about twice the concentration in the liver suggests that much development is needed to consider NTSR1 as a promising biomarker for dual-labeled compounds." (PMID 40005958, 2025). "NTSR1 abnormal expression by cancer cells makes it a strategic target for antitumoral therapies, such as compounds that use NTSR1 binding probes to deliver cytotoxic agents to tumor cells." (PMID 36949141, 2023). "Our team has shown that NTSR1 expression levels are correlated with the grade and prognosis of cancer in several tumors, especially in endometrial and ovarian adenocarcinomas, with its cytoplasmic localization increasing with the grade of the tumor." (PMID 36902025, 2023). "An NTSR1 antagonist SR48692 could hinder tumor growth in triple-negative cancer cells (MDA-MB-231) xenografted in nude mice." (PMID 36294386, 2022). "NTSR1 revealed frequent tumor-specific hypermethylation in CA-CRC and LS." (PMID 34680073, 2021). "The authors concluded that these agents may help identify NTR-positive lesions and predict which patients and individual tumours are likely to respond to novel interventions targeting NTSR1." (PMID 32336282, 2020). "NTSR1 is involved in tumor progression in many cancers, including digestive cancers." (PMID 33268796, 2020). "Similarly, NTSR1, which belongs to the large superfamily of G-protein coupled receptors, was shown to promote tumor invasion by accelerating EMT." (PMID 30965637, 2019).
tumor (continued). "Tumoral cells with potential aggressiveness characteristics could be detected with NTS/NTSR1 labeling, and specific treatment could be proposed accordingly." (PMID 25249538, 2014). "Both NTS and NTSR1 were expressed in 20 and 40 % of the tumor breast and lung tumors, respectively." (PMID 25249545, 2014). "From our findings, we propose that patients bearing this complex should be responders to kinase inhibitors, and that inhibition of NTS/NTSR1 complex should reduce the rate of tumor progression, providing a longer therapeutic window for the practitioners to treat their patients." (PMID 25249545, 2014). "In the first case, a non-viral gene transfer particle bearing six NTS molecules covalently bound to poly-lysine, enabled the transfer of a reporter and therapeutic gene to those tumor cells expressing NTSR1 when injected in the tumor or into the blood circulation of xenografted nude mice." (PMID 23335914, 2012). "In addition to MMP11, neurotensin receptor 1 (NTSR1), known to be involved in tumor progression by regulating a series of transforming functions such as cellular migration and invasion, was also selected as a candidate BPA-responsive gene." (PMID 23285176, 2012). "Therefore, NTSR1 expression appears to be linked to tumorigenesis in general and cannot be used as a diagnostic tool to distinguish GIST from other tumor types or to predict their risk of malignancy." (PMID 21364741, 2011). "Furthermore, knockdown of NTSR1 reduces tumour invasion via the Jun/miR-494/SOCS6 axis." (PMID 32336282, 2020). "Our data also suggest that NTSR1 copy number gain may also be related to the invasive tumor growth." (PMID 26334593, 2015). "NTS/NTSR1 may also be considered to become a carrier of chemotherapy drugs for tumor cells." (PMID 23335914, 2012). "NTS binds to its cognate receptor, NTSR1, and activates downstream oncogenic signaling pathways, such as PI3K/Akt, thereby promoting tumor progression." (PMID 41556039, 2026). "Hypermethylation frequency of NTSR1 in CAC versus normal tissue (p = 0.037)Half of the CACs (16/31, 52%) expressed CD274-positive immune cells, whereas tumor cells were CD274-negative." (PMID 41562706, 2026). "Due to its nanomolar NTSR1 affinity, the simple and high-yielding radiosynthesis using the HYNIC precursor 5, and the excellent tumor uptake in vivo (8.8 ± 3.4 %ID/g at 2 h p.i.), we suggest [99mTc]1 as a candidate for clinical translation." (PMID 40574013, 2025). "We included clinical factors including age at diagnosis, gender, tumor pathological grade, lymph node status, distant metastasis, TNM stage, and gene signatures MAP3K19 and NTSR1 expression (high- and low-expression groups divided by median value)." (PMID 36439693, 2022). "The abundances of 22 tumor-infiltrating immune compartments in LUAD samples were systematically recorded by the CIBERSORT algorithm and integrated with MAP3K19 and NTSR1 molecular profiles to analyze the degree of immune infiltration in LUAD." (PMID 36439693, 2022). "Among the five RMScore genes, four (ANLN, KRT6A, PITX3, and NTSR1) were identified to be upregulated, while CYP17A1 was identified to be downregulated in TCGA-LUAD tumor tissues compared with paired normal tissues." (PMID 35859664, 2022). "Among them, a NTSR1 pharmacological antagonist (SR48692) has proved interesting, by inhibiting tumor growth and cancer cell proliferation and survival." (PMID 33268796, 2020). "Blocking NTS signaling with NTSR1 inhibitor in combination with ADT markedly delayed NED development and reduced tumor burden in preclinical models." (PMID 30770901, 2019). "Further work is required to elucidate the detailed mechanisms for epigenetic silencing of NTSR1 and NTSR2 in diverse tumor types." (PMID 26298774, 2015). "When injected into nude mice, we observed an increase in tumor growth and metastasis emergence from cells expressing NTS and NTSR1 as compared to cells expressing NTSR1 alone." (PMID 25249545, 2014).
tumor (continued). "Accordingly, lapatinib, an EGFR/HER2 tyrosine kinase inhibitor, as well as metformin, reduced the tumor growth of cells overexpressing NTS and NTSR1." (PMID 25249538, 2014). "Sustained activation of NTSR1 leads to persistent activation of signaling pathways, including ERK1/2, hence facilitating tumor growth and progression." (PMID 21364741, 2011). "In human tumor these conditions would be satisfied if NTS is synthesized and released within the vicinity of NTSR1 expressing cells." (PMID 19156213, 2009). "Moreover, the administration of the neurotensin receptor 1 antagonist SR48,692 or the silencing of this receptor blocked tumor growth in experimental mice xenografted with MDA-MB-231 BC cells." (PMID 41301028, 2025). "In conclusion, our studies show that enhanced cell uptake and increasing tumor to blood ratios over time displayed the superiority of [55Co] Co-NOTA-NT-20.3 over [68Ga] Ga-NOTA-NT-20.3 and [64Cu] Cu-NOTA-NT-20.3 for the targeting of NTSR1." (PMID 36559218, 2022). "Out of eleven genes, there was insufficient or no data for DPP6 or SEZ6L and NTSR1 in the tumor tissues for which they were identified throughout the study; thus, no comparison was possible." (PMID 35361846, 2022). "The same team also showed that NTSR1 was involved in cellular migration, invasion and induction of matrix metalloproteases-9 (MMP-9) and use of SR48692 (an NTSR1 antagonist) halted tumor growth in triple-negative cancer cells (MDA-MB-231) xenografted in nude mice." (PMID 32336282, 2020). "Although NTSR1 blockage by the systemic administration of its non-peptide antagonist SR 48692 decreases tumor progression, this approach can alter the function of dopaminergic neurons, which are known to express high levels of NTSR1." (PMID 24824754, 2014). "The deregulated expression profile of the NTSR1 was correlated with negative prognostic parameters such as tumor size, the number of invaded lymph nodes, Scarff, Bloom and Richardson's histoprognostic grade, and patient mortality." (PMID 25249538, 2014). "Furthermore, a negative correlation has been shown between NTSR1 activity and overall survival, as well as progression-free survival in EC patients, thereby highlighting the role of NT in tumor aggressiveness." (PMID 39334861, 2024). "If both NTSR1 and EGFR are enriched in the tumor cells, SR48692 and osimertinib may be used." (PMID 37508387, 2023). "Moreover, the presence of “anti-cancer” next to “pro-tumorigenic” within a single tumor only complicates the final conclusion regarding AP-2 role in that cancer (e.g. KRT14 vs GRIA1, SEZ6L, SLC12A5 for AP-2α within PAAD or NTSR1 vs PPEF1 for AP-2γ within LUAD)." (PMID 35361846, 2022). "Therefore, targeted therapies blocking either NTSR1 or IL-8 receptors may be effective to inhibit EMT process, thus preventing tumor progression and metastasis." (PMID 33268796, 2020). "[55Co]Co-NT-CB-NOTA revealed high tumor uptake, high tumor-to-background contrast, and sustained tumor uptake in HT29 tumor models leading the authors to conclude that NT-Sarcage labeled with 55Co/58mCo may be an excellent theranostic pair targeting NTSR-1 positive cancers." (PMID 40842662, 2025). "Regardless of the outcome, NTSR1-bearing cells of healthy peripheral tissues can be protected from the deleterious effects of transgene expression using a cell-specific promoter or a tumor-selective promoter, such as the Mucin-1 promoter, to confine the therapeutic effect within the tumorous cells." (PMID 24824754, 2014). "Within adenocarcinomas, NTSR1 staining was never detected in bronchioloalveolar subtypes or in the bronchioloalveolar component of mixed adenocarcinoma but it was often detected in its invasive compartment, suggesting a role favoring tumor invasion and migration." (PMID 25249545, 2014).
tumor (continued). "In addition, a higher intensity of NTSR1 expression was observed in filtrated adenocarcinomas into and beyond the muscularis propria as compared with tumors that were localized to the mucosa or submucosa, suggesting a contribution of NTS/NTSR1 complex in tumor expansion." (PMID 23335914, 2012).
cancer (63 papers, 2009 to 2026). A tumor composed of atypical neoplastic, often pleomorphic cells that invade other tissues. "NTSR1 signaling has been linked to tumorigenesis in various cancers, such as lung, breast, and colon." (PMID 34680073, 2021). "Studies on other types of cancer show that NT acts via NTSR1 and NTSR3/sortilin which caused epithelial-mesenchymal transition." (PMID 29467963, 2018). "Expression of NTS/NTSR1 on breast tumoral cells creates a cellular context associated with cancer aggressiveness by enhancing epidermal growth factor receptor activity." (PMID 25249538, 2014). "Cancer rates were also significantly reduced in NTSR1-deficient mice compared to wild-type mice." (PMID 28316623, 2017). "High expression of NTSR1 has been found to be associated to poor survival also in other cancers." (PMID 25249545, 2014). "RTKs and GPCRs can act independently to alter cancer growth; however, NTSR1 regulates the tyrosine phosphorylation of RTKs such as the EGFR." (PMID 37508387, 2023). "Functionally, NTSR1 promotes cancer cell migration and invasion through cytoskeletal remodeling, and knockdown of NTSR1 significantly inhibits TOX4-induced migration and invasion." (PMID 37726723, 2023). "Of note, we have shown that NTSR1-low formation is promoted by NTS, the NTSR1 agonist ligand, and also found NTSR1-low to be the most abundant form of NTSR1 in our cancer cells and PDX models." (PMID 36949141, 2023). "In our study, in addition to identifying and validating experimental tools, we used in vitro non tumoral and physiopathologically relevant colorectal (CRC) and pancreatic ductal adenocarcinoma (PDAC) cancer cell models to study NTSR1 biology." (PMID 36949141, 2023). "Peptide GPCRs, such as NTSR1, are present in many cancers, and neurotensin (NTS) stimulates the growth of cancer cells." (PMID 37508387, 2023). "A significant variety of cancers have been found to overexpress NTSR1, including pancreatic, colorectal, and breast cancers, among others." (PMID 36559218, 2022). "Of the subtypes, neurotensin receptor 1 (NTSR1) is preferentially upregulated in cancers and is involved in cancer development and progression." (PMID 36559218, 2022). "Among LS samples, NTSR1, SOCS2, and SOCS1 showed tentatively increased methylation frequencies in carcinomas compared to normal mucosae, but only NTSR1 remained significant after adjustment for multiple testing (p = 0.037)." (PMID 34680073, 2021). "The GPCR family members include the neurotensin receptors, of which there are two subtypes, NTSR1 and NTSR2, which are associated with carcinogenesis, cancer progression, and prognosis." (PMID 31974445, 2020). "The proportion of cancer tissue which stained positively for NTSR1 (H-score > 0) was significantly higher than the proportion of normal epithelium which expressed NTSR1 (70.7% vs 10.7% respectively, p < 0.01, Fisher’s exact test)." (PMID 32764278, 2020). "For one participant, although both cancer tissue and normal epithelium were present on the sections used to stain for NTSR1 and NTSR3, only cancer tissue was present on the section used to stain for NTS." (PMID 32764278, 2020). "The numerous molecular mechanisms through which the NTS/NTSR1 complex mediates oncogenic effects are complex and different in each cancer cell-type and thus they must be more precisely and individually elucidated." (PMID 33268796, 2020). "The expressions of NTSR1 (R = 0.41, p < 0.01) in cancer and normal epithelium were significantly correlated." (PMID 32764278, 2020). "We applied a hard filter to the GSMs and finally selected six genes (CLDN3, DECR2, EVA1B, NME4, NTSR1 and XPNPEP3) associated with epigenetic regulation, differentiation and cancer (Pearson’s correlation test; p-value ≤ 0.001)." (PMID 31040866, 2019). "NTSR1 regulates the EGFR transactivation in numerous cancers including colon, foregut neuroendocrine, lung, and prostate cancer." (PMID 30008698, 2018).